TJP2 (tight junction protein 2)
Description:
Plays a role in tight junctions and adherens junctions (By similarity). Acts as a positive regulator of RANKL-induced osteoclast differentiation, potentially via mediating downstream transcriptional activity (By similarity).
Synonyms: X104; ZO2; ZO-2; C9DUPq21.11; DFNA51; DUP9q21.11; FHCA1; PFIC4
Tractability: Antibody: its Gene Ontology location is reachable by antibodies, with high confidence; UniProt places it where antibodies can reach, with medium confidence; the Human Protein Atlas places it where antibodies can reach. PROTAC: ubiquitination databases record sites on it; its protein half-life has been measured.
Gene: Protein-coding gene on chromosome 9 (69,121,264 to 69,274,615, forward strand). Ensembl gene ENSG00000119139.
Subcellular location: Cell junction, adherens junction; Cell membrane; Cell junction, tight junction; Nucleus
Subcellular location (Human Protein Atlas): Cell Junctions; Plasma membrane; Nucleoplasm
Pathways (Reactome):
Signal Transduction: RHOA GTPase cycle; RHOB GTPase cycle; RHOC GTPase cycle; Signaling by Hippo
Programmed Cell Death: Apoptotic cleavage of cell adhesion proteins
Gene Ontology:
Molecular function: cadherin binding; identical protein binding; protein binding; protein domain specific binding; protein tyrosine kinase binding; protein-macromolecule adaptor activity; cell adhesion molecule binding; GMP kinase activity
Biological process: establishment of endothelial intestinal barrier; homotypic cell-cell adhesion; intestinal absorption; positive regulation of blood-brain barrier permeability; regulation of membrane permeability; cell-cell adhesion; cell-cell junction organization; maintenance of blood-brain barrier; protein localization to cell-cell junction; GDP metabolic process; GMP metabolic process
Cellular component: bicellular tight junction; cell junction; cell-cell contact zone; nucleus; plasma membrane; cytosol; nucleoplasm; adherens junction; tight junction
Genetic constraint (gnomAD): Loss-of-function variants: 83 observed, 120.75 expected, observed/expected ratio (o/e) 0.69, 90% interval 0.57 to 0.82. The upper end of that interval is the gene's LOEUF score, 0.82, which puts it in group 3 of 6, group 1 being the genes least tolerant of losing a copy. Missense variants: 1,498 observed, 1,566.9 expected, observed/expected ratio (o/e) 0.96, 90% interval 0.92 to 1. Synonymous variants: 582 observed, 581.75 expected, observed/expected ratio (o/e) 1, 90% interval 0.93 to 1.07.
Gene-disease validity (ClinGen):
ClinGen rates the evidence that TJP2 causes each of these diseases.
nonsyndromic genetic hearing loss (autosomal dominant): Limited.
Homologues: Orthologues: chimpanzee TJP2 (98% identical), macaque TJP2 (96% identical), dog TJP2 (88% identical), pig TJP2 (87% identical), mouse Tjp2 (85% identical), rabbit TJP2 (84% identical), rat Tjp2 (84% identical), guinea pig TJP2 (81% identical), zebrafish tjp2b (58% identical), zebrafish tjp2a (56% identical), Drosophila melanogaster pyd (31% identical), Caenorhabditis elegans zoo-1 (25% identical). Paralogues in human: TJP1 (47% identical), TJP3 (33% identical), DLG5 (19% identical).
Diseases named in the same sentence as TJP2 in open-access papers:
TJP2 is named in the same sentence as 109 diseases in open-access papers, as found by Europe PMC text mining. Sharing a sentence is not in itself a finding about the gene and the disease. The quoted sentences say what the papers report.
cholestasis (17 papers, 2013 to 2025). Impairment of the bile flow caused by obstruction within the liver, or outside the liver in the bile duct system. "In particular, USP53 contributes to the maintenance of tight junction integrity through interactions with TJP1 and TJP2, and its loss leads to canalicular membrane instability and cholestasis." (PMID 41356217, 2025). "The PFIC registry in India examined the correlation between genotype and clinical course and prognosis amongst children with TJP2 deficiency-related cholestasis." (PMID 39697951, 2024). "They showed that the Tjp2-deficient liver has mild progressive cholestasis with lower gene expression levels of bile salt export pump (Bsep) and detoxification enzyme, Cyp2b10, which is aggravated by a cholic acid diet." (PMID 35284810, 2022). "It has been postulated that the bile–blood barrier in the liver of patients with TJP2 deficiency is compromised, thus leading to progressive cholestasis." (PMID 35284810, 2022). "In the mouse, constitutive or inducible deletion of Tjp2 in the liver only leads to mild progressive cholestasis, but these animals are more susceptible to dietary CA." (PMID 36151109, 2022). "The truncating mutations in tight junction protein 2 (TJP2) cause progressive cholestasis, liver failure, and hepatocyte carcinogenesis." (PMID 35284810, 2022). "•Deficiency of tight junction protein 2 (TJP2) causes progressive cholestasis in infants, and the pathophysiology remains unclear." (PMID 35284810, 2022). "We hypothesise that TJP2 deficiency causes cholestasis by disrupting the formation of functional bile canaliculi." (PMID 35284810, 2022). "However, other genetic defects (eg, TJP2) also caused cholestasis with low GGT." (PMID 27050426, 2016). "PFIC4, a paediatric cholestasis with low γGT and elevated BAs, is caused by variants in the TJP2 gene, which encodes the protein known as tight junction protein 2 or zona occludens-2 (ZO-2), involved in maintaining cell-to-cell adhesion." (PMID 39984942, 2025). "Collectively, these results suggest TJP2 deficiency in iHep resulted in impaired directional bile acid transport coinciding with lower TEER, resembling the patient with cholestasis with TJP2 mutation." (PMID 35284810, 2022). "The risk of cholestasis in pregnancy has been associated with genetic variants in ABCB4, ABCB11, ATP8B1, ABCC2, and TJP2 genes." (PMID 34557220, 2021). "Notably, while comprehensive genetic screening excluded mutations in other cholestasis-associated genes (ABCB4, FXR, TJP2, MYO5B, and USP53), both cases carried the p.A1028A concurrently with p.V444A." (PMID 40776909, 2025). "TJP2 mutations prevent CLDN1 from localizing to this membrane, reducing its integrity and allowing toxic bile acids to leak into hepatocytes and cause damage and cholestasis." (PMID 39697951, 2024). "Recent literature report that cholestasis may also be related to mutations in genes encoding bile acid metabolic transporters such as ABCB11, ABCB4, ABCCC2, ATP 8B1, TJP2, which result in the abnormal function of bile salt export pump in hepatocytes." (PMID 38191339, 2024). "After 4 weeks on the DDC diet, however, the Tjp2 cKO mice presented with significantly less severe cholestasis and liver injury and better liver function as compared to corresponding controls, suggesting the development of tolerance to the detrimental effects of DDC." (PMID 36151109, 2022). "In both models, mouse liver with the liver-specific knockout of Tjp2 did not recapitulate the severe neonatal cholestasis of human TJP2 deficiency." (PMID 35284810, 2022). "This is the first reported case of a clinical entity resembling BRIC with a heterozygous mutation in TJP2, without associated mutations in other cholestasis-related genes." (PMID 37205944, 2021). "Additional bile ducts generated by this ductular reaction likely contribute to the tolerance of Tjp2 cKO mice to prolonged DDC diet by facilitating clearance of toxic bile acids from the liver and relieving cholestasis." (PMID 36151109, 2022).
cholestasis (continued). "Liver-specific deletion of Tjp2 in the mouse (Tjp2 cKO mice) leads to mild progressive cholestasis without an overt degradation of the bile-blood barrier (BBB)." (PMID 36151109, 2022). "In TJP2 variants, the claudine CLDN1 fails to position itself at the bile duct membrane, causing the reflux of toxic BAs into hepatocytes, hepatocyte damage, and cholestasis." (PMID 39984942, 2025). "Cholestasis severity, assessed by AP levels, was lower in DDC-diet-fed Tjp2 cKO mice and did not worsen with time as compared to corresponding control animals." (PMID 36151109, 2022).
hearing loss (11 papers, 2014 to 2025). "Since another autosomal dominant missense variant in the gene TJP2 was identified in a Caucasian female with sensorineural hearing loss and bilateral EVA recently, further studies need to be done to evaluate the pathogenicity of this variant." (PMID 40426046, 2025). "A case of sporadic non-syndromic hearing loss with a homozygous TJP2 variant has also been reported." (PMID 40121402, 2025). "Biallelic variants in TJP2, the human orthologue of Tjp2, cause hearing impairment and low-GGT intrahepatic cholestasis, with elongated hepatocyte–hepatocyte tight junctions." (PMID 34681012, 2021). "The Tjp2 gene is mainly expressed in the membrane between the HCs and SCs, and mutation of the Tjp2 gene causes hearing loss." (PMID 28491023, 2017). "Among the samples screened for the TJP2 gene, the three individuals with hearing loss who carried the c.3562A>G (p.T1188A) variation were I-2 (age, 62 years) and II-1 (age, 37 years) of the KNUF25 family and II-6 (age, 57 years) of the YS-149 family." (PMID 24752540, 2014). "However, a novel heterozygous variant (c.1590T>G, p.D530E) in TJP2, a known causal gene for hearing-loss, was also detected in the patients." (PMID 34912366, 2021). "Defects in multiple tight junction‐related proteins, such as ZO‐2 (TJP2), claudin‐9 (CLDN9), claudin‐14 (CLDN14), and claudin‐11 (CLDN11) are associated with hearing loss in humans and mice." (PMID 37691516, 2023). "Our findings expand variant spectrums of hearing loss candidate genes, and shed new insights of pathogenetic effects of ATP6V1B2, TJP2, and KIF11 on hearing functions." (PMID 34912366, 2021). "Our findings expand the variant spectrum of hearing-loss-associated genes and provide new insights on understanding of hearing-loss candidate genes ATP6V1B2, TJP2, and KIF11." (PMID 34912366, 2021). "In the present study, we conducted genetic analyses of the TJP2 and CLDN14 genes in 87 unrelated patients with ADNSHL and 48 unrelated patients with either ARNSHL or potentially sporadic hearing loss." (PMID 24752540, 2014). "This patient has no family history of hearing loss; therefore, either the mutation occurred de novo or hearing loss was incompletely penetrant in this family, as described for another TJP2 variant." (PMID 40121402, 2025). "Our findings suggest that whereas two variations in the TJP2 gene are casually linked to hearing loss, variations in the CLDN14 gene do not make a major contribution to the etiology of hearing loss in Korean patients." (PMID 24752540, 2014).
breast carcinoma (8 papers, 2014 to 2025). "Besides, several lines of evidence suggested that TJP2 expression is silenced in multiple carcinomas, including breast carcinoma, pancreas adenocarcinoma and as well as in a hypoxia-resistant cancer cell lines derived from a scirrhous gastric carcinoma." (PMID 36966163, 2023).
Cholestatic liver disease (7 papers, 2019 to 2024). "Tight junction protein 2 (TJP2) deficiency is caused by a mutation in the TJP2 gene, and defects in tight junctions, leading to severe cholestatic liver disease and extrahepatic manifestations." (PMID 35024979, 2022). "Reported patients with TJP2 deficiency display severe progressive cholestatic liver disease in early childhood, which increases the risk of developing hepatocellular carcinoma." (PMID 34504838, 2021). "Since F11r-/- mice are highly susceptible to liver injury and since deficiency of other tight junction proteins, namely tight junction protein 2 and claudin-1, is associated with cholestatic liver disease, to explain the proband ́s phenotype as a consequence of JAM1 deficiency tempted us." (PMID 37471416, 2023). "TJP2/ZO-2-inactivating mutations in humans cause progressive cholestatic liver disease." (PMID 36151109, 2022). "However, genetic testing through whole exome sequencing identified a novel compound heterozygous variation, a novel in exon 5 and exon 4 of the Tight-Junction Protein 2 gene, and confirmed the diagnosis of cholestatic liver disease as progressive familial intrahepatic cholestasis type 4." (PMID 39697951, 2024). "People with TJP2 variants had ICP (n = 3 out of 103 women in the analysis), gallstone disease (n = 8), previously reported cholestatic liver disease phenotype (n = 4), and 22 did not have a previously reported phenotype." (PMID 37208429, 2023).
gastric cancer (7 papers, 2010 to 2025). A primary or metastatic malignant neoplasm involving the stomach. "The expression of TJP-2 has also been found to be downregulated in various carcinomas, such as breast and pancreatic as well as in hypoxia-resistant cancer cell lines derived from scirrhous gastric carcinoma." (PMID 38255907, 2024).
intrahepatic cholestasis (7 papers, 2017 to 2024). A cholestasis characterized by impairment of the bile flow caused by obstruction located in the liver. "Of 278 patients with intrahepatic cholestasis secondary to genetic cause, 44 cases (15.8%) were identified to have TJP2 mutation." (PMID 39697951, 2024). "In HGMD, 59 different variants in TJP2 were linked to several conditions, such as intrahepatic cholestasis, hypercholanemia, and hearing loss." (PMID 34912366, 2021). "In recent years, genetic testing has allowed for discovery of a variety of homozygous or compound heterozygous TJP2 mutations associated with progressive familial intrahepatic cholestasis and intrahepatic cholestasis of pregnancy." (PMID 37205944, 2021). "In addition, less severe TJP2 mutations have been reported in intrahepatic cholestasis of pregnancy." (PMID 39697951, 2024). "Further analysis of the trio-WES of the family 1 revealed that the affected mother and son also carried a variant (c.1590T>G, p.D530E; g.108844T>G; chr9:71845067T>G) in the TJP2 gene (GenBank: NM_004817), a known candidate gene for intrahepatic cholestasis and sensorineural hearing loss." (PMID 34912366, 2021).
liver disease (7 papers, 2018 to 2024). "Clinical studies have demonstrated that TJP2 mutations increase the risk of severe liver disease, cirrhosis, or liver cancer in adolescents and adults." (PMID 37324459, 2023). "The condition presents in various ways, including mild non-jaundiced illness, recurring jaundice, and severe progressive liver disease in some Amish patients with familial hypercholanemia, a single incompletely penetrant homozygous missense mutation that affects both isoforms of TJP2." (PMID 39697951, 2024). "This review will thus explore how three genes that are associated with liver disease in childhood (ABCB11, TJP2 and VPS33B) might play a role in the initiation and progression of HCC." (PMID 36010647, 2022). "We investigated a genetic liver disease, progressive familial intrahepatic cholestasis (PFIC), which causes severe liver disease in newborns and infants due to a lack of gene called TJP2." (PMID 35284810, 2022).
hepatocellular carcinoma (6 papers, 2018 to 2025). A malignant tumor that arises from hepatocytes. "The higher risk of hepatocellular carcinoma (HCC) associated with PFIC is related to tight junction protein (TJP2) gene mutation." (PMID 39697951, 2024). "The dysregulated cancer-associated pathways caused by the deficiency of TJP2 protein might be attributable to the development of hepatocellular carcinoma." (PMID 34504838, 2021). "Mutations in TJP2 cause the formation of hepatocellular carcinoma in childhood." (PMID 34041244, 2021).
familial intrahepatic cholestasis (5 papers, 2019 to 2022). An instance of intrahepatic cholestasis that is caused by an inherited modification of the individual's genome. "Another case of compound heterozygous mutations in TJP2 predicted to abolish TJ protein translation was observed in a young child with familial intrahepatic cholestasis." (PMID 31450555, 2019). "Genes associated with familial intrahepatic cholestasis (FIC) include ATP8B1 (FIC1), ABCB11 (FIC2), ABCB4 (FIC3), TJP2 (FIC4), NR1H4 (FIC5) and MYO5B (FIC6)." (PMID 33557414, 2021). "In children with familial intrahepatic cholestasis, a condition where bile does not flow through the intrahepatic ducts of the liver, homozygous protein truncating mutations in TJP2 leading to a complete absence of the protein were detected." (PMID 31450555, 2019).
glioblastoma (4 papers, 2019 to 2024). The most malignant astrocytic tumor (WHO grade IV). "Notably, patients with incompletely enhanced glioblastoma multiforme (GBM), who exhibit an increased survival rate, display higher levels of TJP-2 expression than those with completely enhanced GBM, which is associated with shortened survival." (PMID 38255907, 2024).
autosomal dominant non-syndromic hearing loss (3 papers, 2014 to 2021). "The TJP2 gene, mutation of which causes autosomal dominant non-syndromic hearing loss (ADNSHL), lies at the DFNA51 locus on chromosome 9." (PMID 24752540, 2014). "A previous study of an Israeli population revealed that mutations of the TJP2 gene led to autosomal dominant non-syndromic hearing loss (ADNSHL)." (PMID 24752540, 2014). "Interestingly, in humans, autosomal dominant non-syndromic hearing loss is associated with mutations in the TJP2 gene that codes for ZO-2." (PMID 34685547, 2021).
bladder cancer (3 papers, 2022 to 2026). "TJP1 and TJP3 had a 2.5–4% amplification ratio and TJP2 has a 5% mutation ratio in bladder cancer patients." (PMID 35087173, 2022). "In this study, we investigated whether the ZO family (TJP ZO1, ZO-2, and ZO-3, encoded by the TJP1, TJP2, and TJP3 genes, respectively) is associated with the malignant phenotype in bladder cancer." (PMID 35087173, 2022). "For bladder cancer, a perfect score (100%) was found for both sensitivity and specificity in the SOX1, TJP2, MYOD, HOXA9_1, and HOXA9_2 panel." (PMID 40141826, 2025). "The genetic alterations of the TJP family in bladder cancer, examined using cBioPortal, showed that the genetically altered ratios of TJP1, TJP2, and TJP3 were 3%, 3%, and 1.7%, respectively." (PMID 35087173, 2022). "We also found TJP2 and TJP3 mRNA expression positively correlated with chemoresistance in bladder cancer cell lines." (PMID 35087173, 2022). "We found TJP2 expression was positively correlated with IC50 of cisplatin, and TJP3 expression was positively correlated with IC50 of mitomycin C in bladder cancer cell lines." (PMID 35087173, 2022).
lung carcinoma (3 papers, 2021 to 2024). "This abnormal localization of TJP-2 is associated with the disruption of the blood–testis barrier and the invasive characteristics of lung cancer cells in vitro." (PMID 38255907, 2024).
progressive familial intrahepatic cholestasis (3 papers, 2016 to 2022). Progressive familial intrahepatic cholestasis (PFIC) refers to a heterogeneous group of autosomal recessive disorders of childhood that disrupt bile formation and present with cholestasis of hepatocellular origin. "Progressive familial intrahepatic cholestasis (PFIC) types 1, 2 and 3 are a group of cholestatic conditions caused by mutations in ATP8B1, ABCB11 and ABCB4 respectively, and defects in TJP2, encoding tight junction protein 2, can also cause severe cholestatic liver disease." (PMID 26888176, 2016).
asthma (2 papers, 2022 to 2024). "Alternatively, TJP2, a marker associated with maintenance of tight junctions was significantly (p < 0.05) increased in the IL-13 phenotype, suggesting that HBEC with an asthma-like phenotype may only be able to maintain previously developed tight junctions." (PMID 38706568, 2024).
colorectal cancer (2 papers, 2019 to 2023). A primary or metastatic malignant neoplasm that affects the colon or rectum. "TJP2-Alu transcript is more highly expressed in normal tissues compared to tumors of the liver, uterus, and breast, however, colon tumor tissue displays a strong expression of TJP2-Alu transcript not present in normal tissue, making it a potential biomarker for colorectal cancer diagnosis." (PMID 31450555, 2019).